TPH2 (tryptophan hydroxylase 2)
Diseases named in the same sentence as TPH2 in open-access papers (continued):
Sharing a sentence is not in itself a finding about the gene and the disease.
vitamin D deficiency (1 paper, 2022). A nutritional condition produced by a deficiency of VITAMIN D in the diet, insufficient production of vitamin D in the skin, inadequate absorption of vitamin D from the diet, or abnormal conversion of vitamin D to its bioactive metabolites. "Furthermore, in the process of tryptophan synthesis of serotonin, tryptophan hydroxylase-2 can be activated by vitamin D; therefore, vitamin D deficiency can lead to a decrease in serotonin synthesis, which further affects MT synthesis." (PMID 36213197, 2022).
psychiatric disorder (35 papers, 2005 to 2025). A disorder characterized by behavioral and/or psychological abnormalities, often accompanied by physical symptoms. "The present study will contribute to understanding the mechanisms by which childhood trauma and TPH2 polymorphism both play important roles in the development of psychiatric disorders." (PMID 38093326, 2023). "Further research will be needed on the possible application of this treatment for psychiatric diseases involving a Tph2 dysfunction or serotonin deficiency." (PMID 34625528, 2021). "In most psychiatric diseases, the neurotransmitter serotonin shows an increase in the brain and is considered to be a major therapeutic target, implying that activation of TPH2 would be associated with the pathogenesis of human psychiatric disorders." (PMID 35010941, 2021). "As the reaction catalyzed by TPH2 is the rate-limiting step of serotonin biosynthesis, mutations in TPH2 have been associated with several psychiatric disorders (PD)." (PMID 32119710, 2020). "Since the identification of TPH2, there have been numerous association analyses between TPH2 gene variants and psychiatric diseases." (PMID 21886586, 2011). "Numerous studies have identified associations of single nucleotide polymorphisms (SNPs) in the human TPH2 gene with psychiatric diseases." (PMID 20126463, 2010). "As brain 5-HT biosynthesis is regulated by TPH2, and TPH2 SNPs increase the risk for psychiatric disorders, we decided to further analyze the polymorphic variability of the human TPH2 gene and focused on its coding region." (PMID 20126463, 2010). "Yet, some TPH2 polymorphisms have been reported in the literature within the context of psychiatric disorder related endpoints such as antidepressant response and GABA concentration, conditions in which effects of serotonin are underlying biological mechanisms." (PMID 37789226, 2023). "Understanding the effects of TPH2 mutations on protein structure and function may lead to improvements in existing treatments for psychiatric disorders and facilitate the design of further experiments." (PMID 32119710, 2020). "It has been suggested that alteration in TPH2 gene expression might result in central serotonergic system dysfunction, which may in turn lead to abnormality of behavior and increased susceptibility to psychiatric disorders such as TS." (PMID 23360517, 2013). "The human tryptophan hydroxylase 2 (TPH2) gene is one of the most promising candidate genes in numerous psychiatric disorders." (PMID 38093326, 2023). "TPH2 is a potential target for psychiatric disease treatment due to its critical role in 5-HT neurotransmission as a rate-limiting enzyme." (PMID 37242280, 2023). "Thus, considering that these parameters are determinant for protein interactions, the alterations observed throughout the MD simulations may be related to the functional impairment of TPH2 upon P206S, R303W, and R441H mutations, as well as their involvement in psychiatric disorders." (PMID 32119710, 2020). "Evidence also exists to indicate a relationship between TPH2 (Tryptophan hydroxylase 2) alternative splicing and RNA editing in psychiatric diseases." (PMID 28009993, 2017). "Clinical studies suggest gender differences in the associations observed between psychiatric disorders and functional polymorphisms of 5-HT transporter (5-HTT) and tryptophan hydroxylase-2 (TPH2)." (PMID 21760962, 2011). "Overwhelming evidence now points to TPH2 as a candidate gene for 5-HT-related psychiatric disorders." (PMID 20126463, 2010). "The rate-limiting enzyme of serotonin biosynthesis, TPH2, is one of the most promising candidate genes for psychiatric disorders." (PMID 20738857, 2010).
psychiatric disorder (continued). "DNA methylation of genes coding for key regulators of the serotonin system, such as the serotonin transporter (SLC6A4) and the tryptophan hydroxylase 2 gene (TPH2), has been proposed as a possible gene-by-environment mechanism involved in several psychiatric disorders, including MDD." (PMID 38802956, 2024). "TPH2 is a monoamine neurotransmitter that plays a critical role in modulating various physiological processes and has been widely debated as a promising candidate gene in many psychiatric disorders." (PMID 38093326, 2023). "In addition, suicidal patients with psychiatric disorders and relevant life events had higher plasma concentrations of TPH2 and proBDNF than healthy controls." (PMID 37509026, 2023). "Although the effect of the single TPH2 gene on psychiatric disorders has been found in many studies, it is widely acknowledged that environmental risk factors may play an important role in the pathophysiology of mental illness." (PMID 38093326, 2023). "In animal experiments, deficits and excess of TPH2 activity may induce significant behavioral disturbances and catalepsy, whereas the human TPH2 gene is related to psychiatric disorders." (PMID 35185808, 2021). "Thus, the studies have focused on the role of brain-specific TPH-2 in the pathophysiology of various psychiatric disorders, including ADHD." (PMID 27871272, 2016). "Plasma IL-6 was also positively correlated with tph2 mRNA expression in the dorsomedial DR (cDRD), corroborating the hypothesis that proinflammatory cytokines interact with dysregulated neuronal function in psychiatric disease." (PMID 29520369, 2018). "Thus, the activation of TPH2 may open new perspectives for the treatment of neurological and psychiatric disorders through alterations of the serotonin levels in the brain." (PMID 30038568, 2018). "Enzymes involved in serotonin synthesis, such as tryptophan hydroxylase 2 (TPH2, the central isoform), are also critical in understanding psychiatric disorders." (PMID 40806257, 2025). "As the rate-limiting enzyme for the synthesis of central 5-HT, tryptophan hydroxylase 2 (TPH2) is a key player in the modulation of 5-HT neurotransmission and is thus a potential target for therapeutic treatment of psychiatric disorders." (PMID 28771175, 2017). "In addition, we analyzed changes in TPH2, BDNF, and GDNF in mental illness suicide (PI) and life event suicide (LE)." (PMID 37509026, 2023).
infection (7 papers, 2022 to 2024). The state of being infected such as from the introduction of a foreign agent such as serum, vaccine, antigenic substance or organism. "The infection rate of these viruses was approximately 82.1% and the specificity of the Tph2 promoter was approximately 73.8%." (PMID 37165344, 2023). "A relative fold increase of this magnitude would be consistent with HSV activating suppressed TPH2 gene expression following infection." (PMID 35391733, 2022). "Based on these findings, we hypothesized that the infection of TPH2-positive cells with SARS-CoV-2 induces neuronal cell death, thereby causing a decrease in TPH2 expression." (PMID 39475992, 2024). "However, even in the setting of infection, the Tph2 KO animals had reduced gut motility compared to the WT mice." (PMID 39455564, 2024). "In conclusion, infection of SARS-CoV-2 in TPH2-positive cells of the brain VTA may result in increased phosphorylation of tau through activation of GSK3β, induction of neuronal cell death, suppression of TPH2 expression, and decreased serotonin synthesis." (PMID 39475992, 2024). "We show that although descending TPH2-expressing neurons are not resistant to infection from G-protein-deficient rabies viruses, they are rarely traced transsynaptically from dorsal horn neurons." (PMID 36752606, 2023).
tumor (5 papers, 2019 to 2025). "Gut microbiota-derived metabolites, such as isovalerate, amplify neuronal–tumor crosstalk by upregulating tryptophan hydroxylase 2 (Tph2), increasing 5-HT synthesis." (PMID 40243726, 2025). "Moreover, the Authors found that the main source of 5-HT induced by tumor presence originates from enteric neurons expressing tryptophan-hydroxylase 2 (TPH2)." (PMID 38203748, 2024). "TPH2, which is normally expressed in enteric neurons, was indeed absent in both normal and tumor tissue." (PMID 31416966, 2019). "However, reduced tumor number and load of DSS/AOM-induced tumors were also observed in Tph1 KO mice (without statistical significance), and this reduction was significant in DKO (Tph1 and Tph2 KO) mice, suggesting that EC cells may also participate in CRC progression." (PMID 36408175, 2022).
cancer (3 papers, 2017 to 2025). A tumor composed of atypical neoplastic, often pleomorphic cells that invade other tissues. "We have here identified four genes—Tph2, Sspo, Pole, and Ptprq—whose expression in the brain microenvironment was associated with metastasis of cancer cells." (PMID 28210624, 2017). "Mechanistically, isovaleric acid upregulates Tph2 in intestinal serotonergic neurons, increasing 5-HT production, which activates the HTR1B/1D/1F-Wnt/β-catenin pathway in cancer stem cells (CSCs) to promote self-renewal and tumorigenesis." (PMID 40510674, 2025).
neurodevelopmental disorder (3 papers, 2021 to 2022). A behavioral and cognitive disorder with onset during the developmental period that involves impaired or aberrant development of intellectual, motor, or social functions. "Accordingly, we speculate that excess FA-induced overexpression of Sult1a1 and/or Tph2 might disturb neurotransmitter metabolism, and therefore contribute to neurodevelopmental disorders." (PMID 35010941, 2021). "In a study involving TPH2 knock-out mice, lack of 5-HT affected the normal connections of neurons in the brain, leading to neurodevelopmental disorders." (PMID 35334886, 2022).
neurological disorders (2 papers, 2008 to 2024). "Several trials have investigated various TPH2 polymorphic variants, with rs4570625 showing the strongest association with neurological disorders." (PMID 39768746, 2024).
hematological disease (1 paper, 2008). "Indeed, IPA positioned TPH2 within the top hematological disease pathway containing 12 candidate genes." (PMID 18986552, 2008).
movement disorder (1 paper, 2023). Neurological conditions resulting in abnormal voluntary or involuntary movement, which may impact the speed, fluency, quality and ease of movement. "Another study of 69 patients with FMD showed that the tryptophan hydroxylase 2 (TPH2) gene polymorphism may modulate functional movement disorders, both directly and interactively with childhood trauma." (PMID 37628589, 2023).
TPH2 also shares sentences with these, for which no sentence is quoted: attention deficit-hyperactivity disorder (4 papers); panic disorder (4); alcoholism (3); emotional dysregulation (3); Parkinson disease (3); Alzheimer’s dementia (2); chronic fatigue syndrome (2); personality disorder (2); allergic disease (1); Alzheimer’s disease (1); autism spectrum disorder (1); Autoimmunity (1); Borderline personality disorder (1); brain glioblastoma (1); central nervous system disorder (1); chronic atrophic gastritis (1); cognitive disorder (1); cutaneous T-cell lymphoma (1); Dravet syndrome (1); generalized epilepsy (1); hearing loss (1); Hepatitis C (1); Insulin resistance (1); insulinoma (1); intestinal cancer (1); male infertility (1); malnutrition (1); metabolic disorders (1); methamphetamine dependence (1); multiple sclerosis (1).
A further 15 diseases each share a sentence with TPH2 in 1 paper.